CD4 (CD4 molecule)
Diseases named in the same sentence as CD4 in open-access papers (continued):
Sharing a sentence is not in itself a finding about the gene and the disease.
intracerebral hemorrhage (4 papers, 2013 to 2023). A cerebrovascular disorder characterized by bleeding into one or both cerebral hemispheres including the basal ganglia and the cerebral cortex. "In a mouse model of intracerebral hemorrhage, PD-L1 reduced the number of CD4+ T-cells, decreased cell death, and enhanced the blood–brain barrier integrity." (PMID 36417145, 2023). "Furthermore, since current Treg research mainly concentrated on ischemic rather than hemorrhagic stroke, future studies should broaden their knowledge of FoxP3+CD25+CD4+ Tregs in hemorrhagic stroke, including subarachnoid hemorrhage, intracerebral hemorrhage, and hemorrhagic transformation." (PMID 23983771, 2013).
intrahepatic cholangiocarcinoma (4 papers, 2020 to 2025). A carcinoma that arises from the intrahepatic bile duct epithelium in any site of the intrahepatic biliary tree. "The spatial distribution of immune cells in intrahepatic cholangiocarcinoma (iCC) reveals notable patterns: CD8+, CD4+, and CD3+ T cells primarily surround the tumor, while Foxp3+ T cells sometimes infiltrate it." (PMID 39335203, 2024). "Previous work on the immune landscape in intrahepatic cholangiocarcinoma showed an immunosuppressive environment with low numbers of CD3 and CD4 to be correlated with reduced long-term outcomes and low expression of PD-1 to be associated with an improved oncological survival." (PMID 35565318, 2022).
intrauterine growth restriction (4 papers, 2014 to 2022). "In the other study, placental malaria causes an increased production of the Th1 subset of CD4 T lymphocytes that cause intrauterine growth restriction and preterm birth." (PMID 32099563, 2019). "Maternal HIV-1 RNA load and/or CD4 count have also been associated with LBW, intrauterine growth restriction, or SGA." (PMID 24397463, 2014). "Cluster 2, immune tolerance to semi-isogenic fetal antigens at the maternal-fetal interface is the main focus, including maternal immune system, miscarriage, fetus, fetal growth restriction, maternal fetal interface, immune cell, fetal, hlag, regulatory t cell, treg, cd4, tolerance, immune system." (PMID 36700203, 2022).
Jaundice (4 papers, 2017 to 2023). Yellow pigmentation of the skin due to bilirubin, which in turn is the result of increased bilirubin concentration in the bloodstream. "By using Kaplan–Meier curves, we identified that high CD4+T cell, Th1, and Th17 densities, as well as high Th1, Th2, and Th17 percentages were negatively associated with jaundice-free and improved liver function survival (All p-values were below 0.05)." (PMID 31355166, 2019). "The level of serum total bilirubin of the infants, the levels of CD3+, CD4+, CD8+, IgA, IgG and IgM of the infants, the time of jaundice disappearance and the length of hospital stay, hemoglobin and reticulocyte levels were recorded before treatment and after treatment." (PMID 32953679, 2020).
Lassa fever (4 papers, 2022 to 2025). A viral hemorrhagic fever that is caused by the Lassa virus, which is transmitted by contact with infected rodents; it is characterized by fever, headache, malaise, myalgia, and hearing loss. "Ultimately, the involvement of both CD4 and CD8 T cells for pathogenesis renders ML29 inadequate as an exact surrogate model for acute Lassa fever as LASV pathogenesis appears strictly CD8 T cell mediated." (PMID 36289695, 2022).
Lewy body dementia (4 papers, 2021 to 2023). A progressive form of dementia characterized by the presence of protein deposits called Lewy bodies in the midbrain and cerebral cortex, and loss of cholinergic and dopaminergic neurons. "The immune signature of the CSF has helped in understanding the potential mechanisms of peripheral CD4+ T cell homing to the brain and its contribution to neurodegeneration in Lewy body dementia." (PMID 36211372, 2022).
liposarcoma (4 papers, 2017 to 2025). A usually painless malignant tumor that arises from adipose tissue. "The level of CD4 T cell infiltration was positively associated with the prognosis of patients with dedifferentiated liposarcoma." (PMID 38212774, 2024).
Lymphatic Metastasis (4 papers, 2021 to 2024). Transfer of a neoplasm from its primary site to lymph nodes or to distant parts of the body by way of the lymphatic system. "The percentages of CD3+ and CD4+ T cells were significantly higher in LUSC patients with lymphatic metastasis." (PMID 35116020, 2021). "Similarly, the percentage of CD4+ T cells (p = 0.0596) and NK cells tended to higher in patients with lymphatic metastasis." (PMID 35116020, 2021). "In this study, we observed that patients with lymphatic metastasis exhibited significantly lower levels of CD3+T cells, CD4+T cells, and CD3+CD4−CD8−T cells." (PMID 38263363, 2024). "Compared with the group without lymphatic metastasis, the group with lymphatic metastasis exhibited a significant decrease in the levels of CD3+T, CD4+T, DNT, and LMR (P < 0.05)." (PMID 38263363, 2024).
lymphoblastic lymphoma (4 papers, 2011 to 2024). A lymphoma composed of immature small to medium-sized precursor lymphoid cells (lymphoblasts). "We suggest that similar mechanism could explain how CD4 T cells caused the tumor microenvironment of a lymphoblastic lymphoma to remodel when the tumor oncogene was inactivated, inducing tumor regression." (PMID 35903540, 2022).
lysosomal disorder (4 papers, 2022 to 2025). "Thereafter, we hypothesized that mTOR pathway mediated autophagic-lysosomal disorder might be significantly associated with differing expression levels of CHOP on CD4+ lymphocytes, and the overexpression of CHOP might be statistically correlated with CD4+ T lymphocyte reduction." (PMID 40933998, 2025). "We demonstrate that ex vivo lentivirus‐modified, rapamycin‐conditioned CD4+ T cells can also act as next‐generation cellular delivery vehicles—that is, “micropharmacies”—to disseminate corrective enzymes for multiple lysosomal storage disorders." (PMID 35298086, 2022). "Our study confirmed that CTLA-4 expression on CD4+ cells might also be modulated by mTOR pathway mediated autophagic lysosomal disorder." (PMID 39104530, 2024). "As LC3II was also found to be significantly different, which was a biomarker of mTOR pathway mediated autophagic–lysosomal disorders, we hypothesized that this disorder might be associated with differing expression levels of CTLA-4 on CD4+ lymphocytes." (PMID 39104530, 2024). "This study was designed to illustrate the association between CTLA-4 expression on CD4+ lymphocytes and the occurrence of SAI and prognosis of patients with SAI, and furthermore to clarify the relationship between mTOR pathway mediated autophagic–lysosomal disorder and CTLA-4 expression." (PMID 39104530, 2024).
mammary adenocarcinomas (4 papers, 2012 to 2022). "The complex interplay between T cells and the humoral immune system was demonstrated in the MMTV-PyMT mouse model, where IL-4-expressing CD4 + T lymphocytes indirectly promote invasion and subsequent metastasis of mammary adenocarcinomas." (PMID 29350274, 2018). "In mammary adenocarcinoma, a significant interplay between CD4+ T cells and macrophages in promoting invasion and metastasis has been demonstrated, and it is possible that such interactions may also occur in a subset of GBM." (PMID 22937035, 2012).
mediastinal (4 papers, 2013 to 2023). "Antigen-reactivated CD4+ CTLs also infiltrate lesions in fibrosing mediastinitis and drive inflammatory fibrosis." (PMID 36580373, 2023).
monoclonal gammopathies (4 papers, 2011 to 2024). "Those with monoclonal gammopathies showed additional redistribution of CD4 and CD8 T-cell subsets, as well as of APC." (PMID 34907159, 2021). "Five, of whom 4 were MS patients and one patient suffering from a specific from of peripheral neuropathy with monoclonal gammopathy, were analyzed for CD4+-iATP at the time-points described in the section containing patients' characterics." (PMID 21533133, 2011).
monocytic leukemia (4 papers, 2009 to 2025). "Immature monocytic leukemia cells have been discovered to induce apoptosis in neighboring dysfunctional CD4/CD8+ T cells through the disruption of NADPH production, a process involved in the PARP‐1/PAR pathway." (PMID 39927613, 2025). "The HIV-CRISPR screening method has previously identified restriction factors in THP-1 cells (a CD4+ monocytic leukemia cell line) involved in the interferon response against HIV using a focused CRISPR guide library of interferon-stimulated genes (ISGs)." (PMID 36744886, 2023). "In model 1, the target cells (in which autophagy was analyzed) were either CD4 T cells or the human monocytic leukemia THP1 cell line." (PMID 19492063, 2009). "We tested this scenario in an allogeneic coculture of CD4+ T-blasts from P2, P3, P4, or healthy donors with THP-1 cells (a monocytic leukemia cell line) or PMA-differentiated THP-1-derived macrophages (P-Mφ), with or without HKMTb." (PMID 40446017, 2025).
mucinous carcinoma (4 papers, 2012 to 2025). "Enteric and mixed adenocarcinoma had a higher density trend of immune cells than mucinous adenocarcinoma, especially CD4+ (p = 0.0826) and CD68+ (p = 0.1256) cells." (PMID 35158883, 2022). "In stromal tissues, the densities of CD8+ T cells (p = 0.0008), CD4+ T cells (p = 0.0005), Treg cells (p < 0.0001), CD4+ Teff cells (p = 0.0008), and M2 macrophages (p = 0.0061) were significantly greater in serous carcinoma cases as compared to mucinous carcinoma cases." (PMID 40564014, 2025). "In tumor tissues, FAM111B-positive cells (p = 0.0068), CD8+ T cells, CD4+ T cells, Tregs, CD4+ Teff cells (all p < 0.0001), M2 macrophages (p = 0.0002), and DCs (p = 0.0004) were present at higher levels in serous carcinoma samples relative to mucinous carcinoma samples." (PMID 40564014, 2025).
mycobacterial infection (4 papers, 2016 to 2024). "We used this method to characterize the mechanisms associated with the process and found that in zebrafish, like in humans, the depletion of lymphocytes, especially the CD4+ T cell population, is associated with the impaired control of a latent mycobacterial infection." (PMID 29590635, 2018). "The control of mycobacterial infection by the host relies on an immune response centered in CD4+ T cells that produce the macrophage-activating cytokine IFN-γ." (PMID 31947883, 2020). "A recent study underlined that bi-allelic RORC loss-of-function mutations resulted in the absence of IL-17-producing T cells and defective IFNγ production by circulating γδ T cells and CD4+CCR6+CXCR3+ αβ T cells, and was associated with mycobacteriosis." (PMID 27409590, 2016). "Considering the functional similarities between human and zebrafish CD4+ and CD8+ T cells, CD4+ cells could be a key player in controlling a latent mycobacterial infection also in the zebrafish." (PMID 29590635, 2018). "Indeed, CD4 T cell responses to Mtb are contained in a CXCR3+CCR6+ Th subset, cells that produce IFNγ, IL-2 and TNFα, and a mutation leading to the loss of the CXCR3+CCR6+ lineage specific transcription factor RORC leads to mycobacteriosis." (PMID 27409590, 2016). "The depletion of IFN-γ or of upstream cytokines such as IL-12 and IL-18, which are necessary for the maturation of CD4+ T cells into IFN-γ-producing Th1 cells, exacerbates mycobacterial infection." (PMID 31947883, 2020).
Mycoplasma infection (4 papers, 2016 to 2025). "In the present study, PD‐L1 expression on CD14+CD11b+ monocytes and PD‐1 expression on CD4+ T cells was found to be upregulated in bovine mycoplasmosis." (PMID 28544524, 2017). "The median proportion of PD‐1+CD4+ among PBMCs isolated from cattle with mycoplasmosis were higher than those from healthy control cattle." (PMID 28544524, 2017). "Treg cells (CD4+CD25+FoxP3+) preferentially expanded in the host after mycoplasma infection, suggesting that they do play a role in the disease." (PMID 27175511, 2016). "Mycoplasma infection disturbs immune homeostasis, particularly the CD4+/CD8+ T-cell axis." (PMID 40933568, 2025). "Interestingly, the number of PD‐1+CD4+ and PD‐1+CD8+ T cells were negatively correlated with IFN‐γ production from PBMCs in bovine mycoplasmosis." (PMID 28544524, 2017).
mycoplasma pneumonia (4 papers, 2019 to 2025). "By upregulating serum IgA, IgG and IgM levels, enlarging the population of CD4+ T cells and balancing the ratio of CD4+/CD8+ cells, HQH significantly lowered the rate of reinfection in severe pediatric patients of Mycoplasma pneumonia." (PMID 37449208, 2023).
neuropathic pain (4 papers, 2012 to 2023). Chronic pain caused by damage to nerve fibers. "First, to confirm our previous findings, we determined the Foxp3/CD4+ cell ratio in neuropathic pain patients as compared to healthy volunteers." (PMID 27646435, 2016). "Neuropathic pain patients exhibited significantly elevated Foxp3/CD4+ ratios (1.6 ± 0.9 in neuropathic pain vs. 0.8 ± 0.5 in healthy controls; p < 0.05)." (PMID 27646435, 2016). "Our previous studies have indicated that both lumbar spinal cord-infiltrating CD4+ T cells and microglial CD40 contribute to the maintenance of mechanical hypersensitivity in a murine model of neuropathic pain spinal nerve L5 transection (L5Tx)." (PMID 23249743, 2012).
nocardiosis (4 papers, 2012 to 2025). Nocardiosis is a local (skin, lung, brain) or disseminated (whole body) acute, subacute, or chronic bacterial infection. "We recommend that CD4 count be done in every case of nocardiosis to find an association with ICL and further prophylaxis." (PMID 34540476, 2021). "It has been found that approximately 80% of nocardiosis patients have hypoimmunity through CD4 + Th/Ts counting detection, and glucocorticoids are the crucial risk factor for nocardiosis development." (PMID 33243202, 2020). "The association between nocardiosis and solid organ transplantation, HIV infection with CD4 cell count <50/cumm, male gender, steroid therapy, and immunosuppressant therapy has been observed in few studies." (PMID 23320238, 2012). "Evaluation of cell mediates immunity in the form of CD4 count is helpful in the understanding of pathogenesis in cases of nocardiosis without comorbidities." (PMID 34540476, 2021).
oral diseases (4 papers, 2015 to 2020). "Oral diseases by nadir CD4 cell count, current CD4 cell count, or viral load." (PMID 27299992, 2016).
oropharyngeal squamous cell carcinoma (4 papers, 2021 to 2024). "Here, we integrated multiomics approaches to define the phenotypic and molecular profiles of exhausted CD4+ T cells in oropharyngeal squamous cell carcinoma (OPSCC)." (PMID 38868329, 2024). "For example, increased infiltration of CD3+, CD4+, CD8+, FoxP3+, CD20+ and CD56dim was detected in patients with oropharyngeal squamous cell carcinoma and was associated with improved overall survival." (PMID 34823553, 2021). "Unexpectedly, we observed that tumors with increased LLT1+ lymphocyte infiltration had a higher absolute count of CD3+ T cells as well as CD3+ CD4+ T cells (p = 0.0002 and p = 0.0118), which was consistent with a previous study on oropharyngeal squamous cell carcinoma." (PMID 38502058, 2024).
paracoccidioidomycosis (4 papers, 2015 to 2022). A systemic fungal infection caused by Paracoccidioides brasiliensis that is most often seen in immunocompromised patients. "During the course of a paracoccidioidomycosis infection, CD4+ lymphocytes synthesize IFN-γ and IL-12, which hinder the spread of the fungus." (PMID 27303789, 2016). "In human paracoccidioidomycosis (PCM), a study has shown an augmented number of CD4+CD25+Foxp3+ T cells in the lesions and in the peripheral blood of infected patients, and these cells exhibited strong suppressive activity." (PMID 26512987, 2015).
pemphigus vulgaris (4 papers, 2022 to 2024). Pemphigus is a group of chronic autoimmune skin diseases characterized by blister formations on the outer layer of the skin and the mucous membranes. "Here we aimed at characterizing the rapid expression of intracellular CD154 (CD40L) as a marker for rare antigen-specific CD4+ T cells in pemphigus vulgaris (PV)." (PMID 36203615, 2022). "Notably, intense CD4+ and CD8+ T-cell infiltrations were found in the peri-bronchial area in the lungs of PAMS mice, but not in pemphigus vulgaris mice." (PMID 35448168, 2022).
peripheral artery disease (4 papers, 2022 to 2025). "When compared to the literature, published studies showed that PLWHs have a 19% higher risk of developing peripheral artery disease compared to the general population, and the risk doubles in HIV patients with CD4+ < 200 cells/mm3 compared to those with CD4+ ≥ 500 cells/mm3." (PMID 37627941, 2023).
peripheral nerve injury (4 papers, 2012 to 2021). Injury to a peripheral nerve. "This was confirmed by a recent study showing that MHC class II-restricted CD4+ T helper cells contribute to the transition from acute to chronic mechanical allodynia in a rat model of peripheral nerve injury." (PMID 33692810, 2021). "Antigen-specific and MHCII-restricted CD4+ αβ T cells have been shown or suggested to play an important role in the transition from acute to chronic mechanical allodynia after peripheral nerve injuries." (PMID 29544518, 2018). "Moreover, the selective activation of CD4+ αβ T cells among the immune cells in the spleens after peripheral nerve injuries implied a similar pattern of immune cell activation in the local lymph nodes, i.e., selective activation of CD4+ αβ T cells." (PMID 29544518, 2018). "Hence, our lymphadenectomy results can just suggest that CD4+ αβ T cells in the DR leptomeninges should have a role in the development of chronic mechanical allodynia after peripheral nerve injuries." (PMID 29544518, 2018). "Even though, we could conclude that antigen-specific and MHC II-restricted CD4+ αβ T cells selectively enter into the DR leptomeninges along the somatosensory pathways for the transmission of mechanical allodynia after peripheral nerve injuries." (PMID 29544518, 2018). "Interestingly, MHC class II knockout (k/o) mice that lack MHC class II-restricted T helper cells displayed an impaired chronification of mechanical allodynia after peripheral nerve injury, indicating the general importance of CD4+ T helper cells for pain chronification in rodents." (PMID 33692810, 2021). "The noteworthy results here provide the first evidence that CD4+ αβ T cells selectively infiltrate into the DR leptomeninges of the somatosensory pathways transmitting mechanical allodynia and contribute to the transition from acute to chronic mechanical allodynia after peripheral nerve injuries." (PMID 29544518, 2018). "Hence, antigen-specific and MHC II-restricted CD4+ αβ T cells selectively present in the DR leptomeninges might have functional roles in the development of chronic mechanical allodynia after peripheral nerve injuries." (PMID 29544518, 2018). "Further studies showed that in contrast to CD8+ αβ T cells, B cells, NK cells, and macrophages, CD4+ αβ T cells were selectively activated by dendritic cells and polarized to IFNγ-positive, inflammatory Th1 cells in peripheral lymphoid organs, such as the spleen, after peripheral nerve injuries." (PMID 29544518, 2018). "In summary, our data support that lumbar spinal cord infiltrating Th1, and not Th2, CD4+ T lymphocytes mediate the maintenance of peripheral nerve injury-induced neuropathic pain." (PMID 25143871, 2014). "Altogether, our data indicate that both CD4 and CD40 play a role in L5Tx-induced leukocyte infiltration into the lumbar spinal cord but have differential contributions to spinal cord microglial activation following peripheral nerve injury." (PMID 23249743, 2012). "Altogether, data indicate that both CD4 and CD40 play a role in L5Tx-induced leukocyte infiltration into the lumbar spinal cord but have differential contributions to spinal cord microglial activation following peripheral nerve injury." (PMID 23249743, 2012).